ASPH (aspartate beta-hydroxylase)
Diseases named in the same sentence as ASPH in open-access papers (continued):
Sharing a sentence is not in itself a finding about the gene and the disease.
renal carcinoma (2 papers, 2017 to 2025). A carcinoma arising from the epithelium of the renal parenchyma or the renal pelvis. "RCE cell-specific IR-induced SASP factors, such as ALDH18A1 (Log2 ratio 1.43) and ASPH (Log2 ratio 1.20), which are associated with a highly unfavorable prognosis in renal cancers, underscore the tumor-promoting potential of specific SASP factors." (PMID 39858632, 2025). "Highly expressed unfavorable SASP factors, such as ALDH18A1 and ASPH, were identified as key drivers of renal cancer." (PMID 39858632, 2025). "ASPH is detectable at both the transcriptional and protein levels in human cells, including renal cancer cells, and its elevated expression typically correlates with the development and progression of carcinomas." (PMID 39858632, 2025). "Both ALDH18A1 and ASPH exhibited stage-specific alterations in expression, highlighting their potential relevance to renal cancer progression." (PMID 39858632, 2025). "Similarly, ASPH expression levels demonstrated significant alterations across stages I–IV of renal cancer." (PMID 39858632, 2025). "This study offers a novel perspective by identifying ALDH18A1 and ASPH as integral components of the IR-induced SASP, establishing a previously unrecognized link between radiation-induced senescence and renal cancer progression." (PMID 39858632, 2025). "Out of the unique set of genes detected by BNNPT, a few were reported to be relevant to renal cancer or disease: CDCP1, GSTT1, E2F3, MAPK1, SALL4, SIRT1, ADAMTS13, Gfrα1, ASPH, MIR17HG, APOE, BMP4, RCOR1, NUMB and SEC63." (PMID 28986523, 2017).
anemia (1 paper, 2020). A reduction in the number of red blood cells, the amount of hemoglobin, and/or the volume of packed red blood cells. "Given the roles of many 2OG oxygenases, including AspH, in important biological processes, achieving inhibitor selectivity is likely important, especially when treating long term diseases such as anaemia." (PMID 32457455, 2020). "Among the other APIs currently in clinical trials for treating anemia in patients suffering from chronic kidney disease, only the HIF prolyl hydroxylase inhibitor vadadustat inhibited AspH activity substantially (entry 19)." (PMID 32457455, 2020).
bone sarcoma (1 paper, 2025). A sarcoma that arises from the bone. "Therefore, we are interested in studying ASPH in a bone sarcoma model to determine if there is an analogous paradigm." (PMID 40149287, 2025).
Brain atrophy (1 paper, 2022). Partial or complete wasting (loss) of brain tissue that was once present. "Therefore, ethanol-associated brain atrophy and degeneration may be mediated in part by the inhibition of insulin-Akt stimulation of ASPH and attendant CNS cellular senescence and apoptosis." (PMID 35625605, 2022).
cartilage tumors (1 paper, 2025). "As a first step in evaluating ASPH expression in CS, we performed IHC of an annotated TMA and additional cartilage tumors." (PMID 40149287, 2025).
cervical cancer (1 paper, 2022). A primary or metastatic malignant neoplasm involving the cervix. "We showed that high expression of ASPH in cervical cancer is more likely to resist radiotherapy, suggesting that possibly those with high ASPH expression have poor sensitivity to treatment with radiotherapy." (PMID 35965520, 2022). "There are very few studies on ASPH in cervical cancer, one published in vitro study showed that ASPH was positively expressed in 3 specimens in cervical cancer cell lines." (PMID 35965520, 2022). "The positive expression rate of ASPH in cervical cancer cells is about 88.5%." (PMID 35965520, 2022). "There are no relevant studies on its role in cervical cancer and related functional studies on whether there is a difference in ASPH expression in radiotherapy-sensitive and resistant groups." (PMID 35965520, 2022).
cervical squamous cancer (1 paper, 2022). "Our study showed a higher rate of ASPH positive expression in the radiotherapy-resistant group in intermediate to advanced squamous cervical cancer." (PMID 35965520, 2022). "Immunohistochemical results showed that ASPH was more highly expressed in the radiotherapy-resistant group than in the radiotherapy-sensitive group in intermediate and advanced squamous cervical cancer." (PMID 35965520, 2022). "ASPH could be a tumor marker, prognostic indicator, and therapeutic target in squamous cervical cancer." (PMID 35965520, 2022). "Those with high ASPH expression had lower OS and PFS and could be prognostic indicators in intermediate and advanced squamous cervical cancer." (PMID 35965520, 2022). "From survival curves, it can be seen that the low expression of ASPH and high expression of NKAPP1 may lead to increased sensitivity to radiotherapy, thus improving cervical squamous cancer patients’ efficacy." (PMID 35965520, 2022). "We identified two genes, ASPH and NKAPP1, as both genes affecting radiotherapy sensitivity and survival by analyzing the included GEO database on radiotherapy sensitivity in intermediate and advanced squamous cervical cancer, using bioinformatics methods with relevant databases." (PMID 35965520, 2022).
Chlamydia infection (1 paper, 2019). "The remaining 6 proteins identified by all 3 MS approaches–ASPH, LRRF1, LRC59, TMOD3, CLINT1, and BAP31–represent priority targets for further study in the context of Chlamydia infection." (PMID 30943267, 2019).
ductal carcinoma (1 paper, 2019). "ASPH is silenced in normal adult breast, upregulated from in situ malignancies to highly expressed in invasive/advanced ductal carcinoma." (PMID 31694640, 2019).
endometrial cancer (1 paper, 2021). Primary or metastatic malignant neoplasm involving the endometrium (mucous membrane that lines the endometrial cavity). "For instance, miR-135a was found to suppress the progression of endometrial cancer through targeting ASPH." (PMID 33526034, 2021).
gallbladder carcinoma (1 paper, 2025). "Results from Mendelian randomization studies suggest that heightened ASPH levels play a significant role in the development of gallbladder polyps and stones, which are established clinical risk factors in gallbladder cancer." (PMID 40110547, 2025). "Further analysis was conducted to examine the association between ASPH and the clinical characteristics of gallbladder cancer, along with its implications on the prognosis of gallbladder cancer patients." (PMID 40110547, 2025). "In gallbladder carcinoma, ASPH promotes the process of cell proliferation, and ASPH is mainly expressed in epithelial of gallbladder carcinoma." (PMID 40110547, 2025). "ASPH expression is notably elevated in gallbladder cancer tissues, correlating with an unfavorable prognosis for patients afflicted with this disease." (PMID 40110547, 2025). "In the present, it’s found that high expression of ASPH promotes epithelial mesenchymal transition and epithelial cell migration in gallbladder cancer." (PMID 40110547, 2025). "ASPH plays a role in promoting the development of gallbladder cancer and resistance to chemotherapeutic agents, rendering it a promising target for therapeutic interventions." (PMID 40110547, 2025). "In Exhausted T cells, the expression of ASPH is highest in liver metastasis of gallbladder cancer, and the expression of ASPH is higher in primary focus of gallbladder cancer than that in lymph node of gallbladder cancer." (PMID 40110547, 2025). "Differential analysis of gallbladder cancer parental cells and metastatic cells from GSE106671 revealed increased ASPH expression in metastatic gallbladder cancer cells." (PMID 40110547, 2025). "The analysis revealed that ASPH influences crucial processes such as the cell cycle, tumor immunity, and cell adhesion, which are integral in gallbladder cancer development." (PMID 40110547, 2025). "Inhibiting the expression of ASPH in gallbladder cancer can improve the treatment response in patients when used in conjunction with clinical therapy." (PMID 40110547, 2025). "In epithelial, the expression of ASPH was highest in primary focus of gallbladder cancer, and the expression of ASPH is higher in lymph node of gallbladder cancer than that in liver metastasis of gallbladder cancer." (PMID 40110547, 2025). "Correlation analysis between ASPH and clinical characteristics of gallbladder cancer revealed that ASPH impacts the differentiation, tumor size, TNM stage, and invasion of gallbladder cancer." (PMID 40110547, 2025). "According to the result of Cellchat, compared with low expression of ASPH, high expression of ASPH significantly downregulates the MHC1 signaling pathway in the tumor microenvironment of gallbladder cancer." (PMID 40110547, 2025). "Gallbladder cancer is also classified as a type of biliary system tumor; however, research on the association of ASPH with gallbladder cancer is currently lacking." (PMID 40110547, 2025). "This further confirms that ASPH affects the differentiation process of gallbladder cancer." (PMID 40110547, 2025). "Furthermore, the impact of ASPH on the microenvironment of gallbladder cancer was revealed through single-cell sequencing, and potential drugs targeting ASPH were analyzed using network pharmacology." (PMID 40110547, 2025). "Therefore, inhibiting ASPH expression in gallbladder cancer is beneficial for enhancing the response rate to immune therapy for gallbladder cancer." (PMID 40110547, 2025). "ASPH plays an important role in the immune abnormalities of gallbladder cancer." (PMID 40110547, 2025). "The gallbladder cancer cell line QBC-SD expresses the ASPH protein." (PMID 40110547, 2025). "Therefore, high expression of ASPH in gallbladder cancer leads to immune therapy tolerance." (PMID 40110547, 2025). "Therefore, it can be seen that ASPH can serve as a target for the treatment of gallbladder cancer." (PMID 40110547, 2025).
gallbladder carcinoma (continued). "Correspondingly, high expression of ASPH significantly reduces the IL1 signaling pathway, complement signaling pathway and IFNII signaling pathway in the tumor microenvironment of gallbladder cancer." (PMID 40110547, 2025). "Therefore, high ASPH expression in gallbladder cancer may lead to immune tolerance." (PMID 40110547, 2025). "According to the result of Cellchat, compared with low expression of ASPH, high expression of ASPH significantly enhances the FN1 signaling pathway and COLLAGEN signaling pathway between epithelial and fibroblast in the tumor microenvironment of gallbladder cancer." (PMID 40110547, 2025). "The single-cell immune microenvironment reveals that ASPH not only enhances the expression of immune checkpoints, namely PDL1 and PVR, in the gallbladder cancer epithelium, resulting in immune evasion, but also triggers epithelial-mesenchymal transition and migration, promoting metastasis." (PMID 40110547, 2025). "Accordingly, high expression of ASPH can activate the four pathways of FN1 signaling pathway, COLLAGEN signaling pathway, VISFATIN signaling pathway and SPP1 signaling pathway, these pathways occur mainly in the epithelial, myeloid cell, myeloid cell and macrophage of gallbladder carcinoma." (PMID 40110547, 2025).
gallbladder polyps (1 paper, 2025). "Using Mendelian randomization and meta-analysis, it was discovered that ASPH promotes the occurrence of gallbladder polyps and gallstones." (PMID 40110547, 2025).
gastric cancer (1 paper, 2023). A primary or metastatic malignant neoplasm involving the stomach. "Our results suggested that ASPH might serve as a candidate biomarker to predict prognosis and a novel therapeutic target for gastric cancer patients treated with neoadjuvant chemotherapy." (PMID 36982561, 2023).
head and neck cancer (1 paper, 2024). A primary or metastatic malignant neoplasm affecting the head and neck. "ASPH inhibitor MO-I-1151 had significant effects on reducing migration and invasion of head and neck cancer cells, both in monolayers and matrix-embedded spheroids." (PMID 38732216, 2024). "We hypothesize that inhibition of ASPH activity could have anti-tumor properties in patients with head and neck cancer." (PMID 38732216, 2024).
head and neck squamous cell carcinoma (1 paper, 2024). A squamous cell carcinoma that arises from any of the following anatomic sites: lip and oral cavity, nasal cavity, paranasal sinuses, pharynx, larynx, and salivary glands. "In this study, we screened tumor tissues of 155 head and neck squamous cell carcinoma (HNSCC) patients for the expression of ASPH using immunohistochemistry." (PMID 38732216, 2024). "Our study documents the upregulation of Aspartate β-Hydroxylase (ASPH) in head and neck squamous cell carcinoma (HNSCC) based on immunohistochemical examination of human tumor tissues." (PMID 38732216, 2024). "ASPH is a documented oncogene in several cancers but has not been studied in head and neck squamous cell carcinoma to our knowledge." (PMID 38732216, 2024).
Heat Stroke (1 paper, 2023). A condition caused by the failure of body to dissipate heat in an excessively hot environment or during PHYSICAL EXERTION in a hot environment. "Thus, genetic variants in the ASPH gene, which encodesa protein that regulates the process of excitation–contractionin muscles, are associated with heat stroke and malignanthyperthermia in humans." (PMID 37867610, 2023).
intrahepatic cholangiocarcinoma (1 paper, 2020). A carcinoma that arises from the intrahepatic bile duct epithelium in any site of the intrahepatic biliary tree. "The first vaccine against ASPH was based on matured dendritic cells (DC) loaded with the ASPH protein and tested in an orthotopic rat model of intrahepatic cholangiocarcinoma." (PMID 32811566, 2020).
leukemia (1 paper, 2021). A malignant (clonal) hematologic disorder, involving hematopoietic stem cells and characterized by the presence of primitive or atypical myeloid or lymphoid cells in the bone marrow and the blood. "Therefore, much interest has been focused on discovery of new tumor- or leukemia-associated antigens, such as ASPH." (PMID 35004304, 2021). "ASPH may have the potential to serve as a tumor- or leukemia-associated antigen for immunotherapy." (PMID 35004304, 2021). "ASPH is expressed on blasts in approximately 40% of AML cases, and may serve as a new therapeutically targetable leukemia-associated antigen." (PMID 35004304, 2021).
myopia (1 paper, 2023). "Finally, one proband (case 7, who had high myopia, spherophakia and soft dysmorphic features) was found to have compound heterozygous changes in ASPH." (PMID 37107549, 2023).
neuroendocrine tumors (1 paper, 2015). "There was substantial ASPH protein expression in 101 of 104 PDACs (97.1%) on tissue microarrays (TMAs), and no immunoreactivity was observed in pancreatitis, normal pancreas, intestine or pancreatic neuroendocrine tumors." (PMID 25483102, 2015).
pneumothorax (1 paper, 2021). Abnormal presence of air in the pleural cavity. "However, it is noteworthy that whether ventricular septal defect and recurrent spontaneous pneumothorax are related to the ASPH mutation remained unknown, because only one patient was found in this consanguineous Chinese family." (PMID 33217155, 2021).
Refsum disease (1 paper, 2025). Refsum disease, biochemically characterised by phytanic acid accumulation, belongs to the group of leucodystrophic diseases. "Clinically observed PAHX variants are associated with Refsum disease (OMIM: 266500), including the R275Q/W PAHX variants, which correspond to the R735Q/W variations in AspH." (PMID 41354343, 2025).
tumor (57 papers, 2007 to 2026). "Higher ASPH expression scores and tumor grade were equivalently associated with a greater risk of death and metastasis." (PMID 40149287, 2025). "Analysis of clinical samples demonstrates a positive association between ASPH expression and indicators of poor differentiation, increased tumor size, advanced TNM stage, lymph node metastasis, and invasion." (PMID 40110547, 2025). "Nanosecond CaEP (nsCaEP) also induced significant expression of aspartate-β-hydroxylase (ASPH), a protein linked to calcium homeostasis and tumor progression." (PMID 39980072, 2025). "What’s more, in HCC, over-expression of ASPH also resulted in its invasiveness and augmented hydroxylase activity of tumor tissues was associated with unfavorable prognoses of patients with HCC." (PMID 38702698, 2024). "Aspartate β-hydroxylase (ASPH) has been identified as one of the cell surface proteins associated with malignant transformation of tumor cells." (PMID 32811566, 2020). "Since ASPH is cell surface displayed on tumor cells, it represents a tumor-associated antigen that can be targeted by both cell-mediated and humoral immunity." (PMID 32811566, 2020). "GBM was associated with the highest levels of ASPH, more abundantly distributed in hypoxic than in normoxic tumor regions." (PMID 31608231, 2019). "The association between ASPH expression and mtDNA stability based on the changes of mtDNA copy number and mutagenesis was analyzed in tumor and matched non-tumor tissues in a cohort of 71 patients with HCC." (PMID 28714949, 2017). "ASPH can lead to carcinogenesis by inducing decreased cleavage of caspase-3, causing inhibition of apoptosis, and may also promote tumor immune escape via inhibition of natural killer (NK)-cell activity." (PMID 35004304, 2021). "Additionally, high ASPH expression has been linked to tumor recurrence, such as in retroperitoneal liposarcoma (RPLS), where it serves as an independent risk factor for recurrence, and has been identified as a potential target regulating tumor cell migration and invasion." (PMID 41312363, 2025). "Additionally, as ASPH was identified as a tumor-associated antigen, immunotherapy approaches, vaccines and monoclonal antibodies, were tested with promising results in preclinical experiments and results of phase I clinical trial with the PAN-301-1 vaccine were published." (PMID 32811566, 2020). "In the field of biomarkers, systemic immune-inflammation index (SII), microRNAs (miRNAs), and aspartate β-hydroxylase (ASPH) are molecular markers that influence chemotherapy sensitivity by modulating the tumor microenvironment or signaling pathways." (PMID 41626148, 2026). "In tumor cells, expression of ASPH is positive with log2 (IC50) of gemcitabine (p=1.1e-12, r=0.26), and the log2 (IC50) of gemcitabine is higher in high expression ASPH tumor cells than that in low expression ASPH tumor cells (p=6.7e-11)." (PMID 40110547, 2025). "scRNA-seq confirmed the improved activation of CD8+ T cells in tumor-infiltrating cells after combined therapy with DNA vaccination and ASPH inhibition." (PMID 40655119, 2025). "Among the six model genes, ASPH, CDKN2A, and NINJ1 exhibited strong correlations with tumor-associated immune cells." (PMID 39980566, 2025). "We demonstrated that ASPH inhibition enhances anti-tumor immunity induced by DNA vaccination in tumors with reversible downregulation of MHC-I molecules." (PMID 40655119, 2025). "Recent studies have highlighted the significance of aspartate-β-hydroxylase (ASPH), a transmembrane protein widely expressed in cancer cells, in tumor progression and calcium homeostasis." (PMID 39980072, 2025). "These investigations will provide novel insights into the interplay between ASPH and anti-tumor immunity, potentially revealing new therapeutic strategies targeting ASPH to enhance immune-mediated cancer control." (PMID 40655119, 2025).